VIM (vimentin)
Diseases named in the same sentence as VIM in open-access papers (continued):
Sharing a sentence is not in itself a finding about the gene and the disease.
Hepatitis (1 paper, 2016). Inflammation of the liver. "In sections of normal, hepatitis, and cirrhotic liver, HPCs, and parenchymal cells did not express αSMA or vimentin (data not show)." (PMID 27881141, 2016).
hidradenoma (1 paper, 2014). A benign epithelial neoplasm arising from the sweat glands. "Immunohistochemical reactivity for CAM5.2, CEA, EMA, S-100, and vimentin in hidradenoma is characteristic." (PMID 24969313, 2014).
Histiocytosis (1 paper, 2024). An excessive number of histiocytes (tissue macrophages). "The stromal-like cells derived from histiocytosis lesions shared fibroblast-like morphology and showed expression of marker typical for mesenchymal cells, i.e. vimentin." (PMID 38342891, 2024).
Hodgkins lymphoma (1 paper, 2014). A heterogeneous group of malignant lymphoid neoplasms of B-cell origin characterized histologically by the presence of Hodgkin and Reed-Sternberg (HRS) cells in the vast majority of cases. "FISH and PCR analyses showed that these two Hodgkin lymphoma-derived hybrid tumors displayed both hamster and human DNA in the same nuclei by FISH, while also retaining the human genes, CD74, CXCR4, CD19, CD20, CD71, CD79b, and VIM." (PMID 25259521, 2014).
homocystinuria (1 paper, 2020). An autosomal recessive inherited metabolic disorder caused by mutations in the CBS, MTHFR, MTR, and MTRR genes. "In addition, VIM expression was found low in the urine of one MMA patient and in two MMA with homocystinuria CblC type patients." (PMID 32679819, 2020).
hydrocele (1 paper, 2024). "None of the specimens of inguinal hernia, hydrocele and UDT showed any vimentin positive smooth muscle." (PMID 38816716, 2024).
Hypercalcemia (1 paper, 2013). An abnormally increased calcium concentration in the blood. "When xenografted into immunodeficient mice, BIN-67 cells developed into tumours that reflected the hypercalcemia and histology of human SCCOHT, notably intense expression of WT-1 and vimentin, and lack of expression of inhibin." (PMID 23433318, 2013).
hypopituitarism (1 paper, 2023). A condition of diminution or cessation of secretion of one or more hormones from the anterior pituitary gland. "Moreover, vimentin and SNAI1 overexpression showed an association with tumors presenting, respectively, headache and hypopituitarism before surgery (p=0.050 and p=0.048)." (PMID 37033229, 2023).
hypovitaminosis D (1 paper, 2025). "Although we had noted a mild increase in the renal expression of fibronectin and vimentin in the Genta VitD— group, we considered that the hypovitaminosis D present in our experimental model was not sufficient to aggravate the renal injury induced by gentamicin." (PMID 40709990, 2025).
Infertility (1 paper, 2013). "LMNA (Lamin A/C), a deficiency of which is associated with infertility in women was down-regulated in the CT and TC groups while VIM, a mesenchymal intermediate filament was up-regulated in the CT group." (PMID 23791816, 2013).
Inguinal hernia (1 paper, 2024). Protrusion of the contents of the abdominal cavity through the inguinal canal. "However, one specimen of inguinal hernia showed desmin positive and vimentin positive myofibroblasts and another specimen of inguinal hernia showed desmin positive and smooth muscle actin positive myofibroblast." (PMID 38816716, 2024).
kidney angiomyolipoma (1 paper, 2014). An angiomyolipoma arising from the kidney. "This study provides the first evidence that tuberin oppositely regulates the expressions of N-cadherin and vimentin in AML renal cells as well as in kidney angiomyolipomas of TSC patients." (PMID 25149531, 2014).
lacrimal gland tumor (1 paper, 2018). "In contrast, distribution of vimentin is abundant in tumor (upper left) than normal region (lower right) and elevated in poorly differentiated (right) than well-differentiated tumor (left), suggesting induction of vimentin according to the aggressiveness of the BRCA1-associated lacrimal gland tumor." (PMID 30652068, 2018).
Leber congenital amaurosis (1 paper, 2016). Leber congenital amaurosis (LCA) is a retinal dystrophy defined by blindness and responses to electrophysiological stimulation (Ganzfeld electroretinogram (ERG)) below threshold, associated with severe visual impairment within the first year of life. "Immunohistochemical assays of the epithelial membrane antigen (EMA), S100, vimentin, KI67, creatine kinase (CK), Leber congenital amaurosis (LCA), CD68, antibodies against glial fibrillary acidic protein (GFAP), BCL2, anaplastic lymphoma kinase (ALK), and synaptophysin levels were performed." (PMID 27917338, 2016).
lepromatous leprosy (1 paper, 2022). A chronic communicable infection which is a principal or polar form of leprosy. "Auto-antibodies against the cytoskeleton intermediate filament protein vimentin have been reported earlier in lepromatous leprosy patients." (PMID 36560940, 2022).
leprosy (1 paper, 2022). Leprosy is a chronic infectious disease affecting primarily the skin and peripheral nervous system. "In a study, differences in the expression of cytoskeleton proteins vimentin and smooth muscle actin in the context of fuso-cellular macrophage transformation were explained to be responsible for hyperchromic indurated nodules in histoid leprosy." (PMID 36560940, 2022). "Furthermore, the predicted BCEs of vimentin may also be useful as a biomarker for the reactions in leprosy." (PMID 36560940, 2022).
Lewy body dementia (1 paper, 2017). A progressive form of dementia characterized by the presence of protein deposits called Lewy bodies in the midbrain and cerebral cortex, and loss of cholinergic and dopaminergic neurons. "On the other hand, VIM, PLP1 and GSTP1 failed to display significant alteration (p > 0.05) between control and either subtypes of Lewy body dementias." (PMID 28800743, 2017).
lipidosis (1 paper, 2019). "Increased amounts were noted for the cytoskeletal proteins vimentin, tropomyosin β chain, aortic smooth muscle actin, α cardiac muscle actin 1, tubulin β chain, MAGP-4, and keratin in the sample of stable atherosclerotic plaques at the stage of lipidosis and fibrosis." (PMID 31703357, 2019).
lipodystrophy (1 paper, 2022). A congenital or acquired disorder characterized by abnormal loss or redistribution of the adipose tissue in the body. "Another link between cell size and vimentin was provided by a recent study showing that Vim −/− mice have deficient accumulation of body fat and by the first report on a human vimentin mutation leading to lipodystrophy." (PMID 36099296, 2022).
lipoma (1 paper, 2019). A benign, usually painless, well-circumscribed lipomatous tumor composed of adipose tissue. "Immunohistochemical analysis of these lipomas revealed that the spindle cells were positive for vimentin and CD34, and negative for S-100 protein and muscle-specific actin." (PMID 31041916, 2019).
lung carcinoid tumours (1 paper, 2025). "Moreover, aberrant expression of VIM is reported in lung carcinoid tumours." (PMID 40812788, 2025).
macular holes (1 paper, 2022). A hole in the macula of the retina. "Traumatic macular hole specimens showed colocalisations of anti-IBA 1 and anti-VIM (Nos." (PMID 34729639, 2022).
MALT lymphoma (1 paper, 2024). An indolent, extranodal type of non-Hodgkin lymphoma composed of small B-lymphocytes (centrocyte-like cells). "Scores for vimentin immunohistochemical staining were 2.18 ± 0.80 in orbital MALT lymphoma (n = 76) and 1.42 ± 0.58 in conjunctival MALT lymphoma (n = 53; p=0.0000012." (PMID 38322414, 2024).
meningoencephalitis (1 paper, 2022). Inflammation of the meninges and brain, generally secondary to an infectious cause. "Consistent with its role in inflammation, VIM was reported to be upregulated in cerebralspinal fluid from children with enterovirus-associated meningoencephalitis." (PMID 35516420, 2022).
mesonephric adenocarcinoma (1 paper, 2019). An adenocarcinoma of the cervix or the vagina arising from mesonephric remnants. "Immunohistochemically, mesonephric adenocarcinoma is usually diffusely and strongly positive for CD10 (apical and luminal), CK7, PAX8, EMA (epithelial membrane antigen), and vimentin." (PMID 31266530, 2019).
Miscarriage (1 paper, 2021). A pregnancy that ends at a stage in which the fetus is incapable of surviving on its own, defined as the spontaneous loss of a fetus before the 22th week of pregnancy. "Interestingly, the expression of VIM in the uteruses of HEV-infected mice that had experienced miscarriage persistently increased relative to that in the uteruses of uninfected mock mice." (PMID 34696377, 2021).
mitral valve disease (1 paper, 2015). "Here, we examine VIC phenotypes in established mouse models of mitral valve disease using SMA, Periostin, Twist1 and Vimentin expression." (PMID 26527432, 2015).
mucinous carcinoma (1 paper, 2025). "Cells were also positive for vimentin, which is usually expressed in endometrioid but not mucinous carcinoma." (PMID 39878900, 2025).
myocarditis (1 paper, 2020). Myocarditis is a condition that is characterized by inflammation of the heart muscle (myocardium). "The anti-vimentin antibodies used in this study are likely to mainly label macrophages in this particular setting of myocarditis, even if it must be recognized that this antibody is not highly specific for this purpose." (PMID 30128917, 2020).
nasopharyngeal tumor (1 paper, 2013). "Similarly, serglycin was inversely correlated with the expression levels of E-cadherin and positively correlated with the expression level of the mesenchymal marker vimentin in primary nasopharyngeal tumor tissues by immunohistochemistry." (PMID 24205138, 2013).
nephritis (1 paper, 2020). Inflammation of renal tissue. "No staining showed significant correlation with the time from the onset of nephritis to the diagnostic renal biopsy (α-SMA: r = 0.22, p = 0.38; vimentin: r = -0.066, p = 0.79; PSGL-1 in glomeruli: r = -0.13, p = 0.62; PSGL-1 in tubulointerstitium: r = 0.065, p = 0.83)." (PMID 31797094, 2020).
Nephropathy (1 paper, 2017). A nonspecific term referring to disease or damage of the kidneys. "In parallel, semi-quantitative immunoblot analysis also showed significant decreased protein expression of fibronectin, collagen IV, vimentin, and α-SMA in mice with established nephropathy after IL-22 gene therapy." (PMID 28726774, 2017).
nephrotic syndrome (1 paper, 2016). A collection of symptoms that include severe edema, proteinuria, and hypoalbuminemia; it is indicative of renal dysfunction. "Increased expression of the intermediate filament protein vimentin in podocytes has previously been shown to occur in other nephrotic syndromes and to be associated with altered podocyte cell signaling, cell shape and adhesion to the GBM." (PMID 26919698, 2016).
neural tumor (1 paper, 2018). "To determine the origin of TDECs in primary patient GBM (p-GBM), we first co-stained for ETV2 with neural stem-like cell markers (Nestin, Vimentin, and CD133) or mature neural tumor cell makers (NeuN and GFAP) in cryosections of p-GBM autopsies." (PMID 29527330, 2018).
neuritis (1 paper, 2020). A neuropathy arising from inflammation of one or more nerves. "Vimentin is another intermediate filament expressed during neuronal differentiation and is involved in stretching of neuritis, whose expression is usually arrested with the stop of the mitotic cycle." (PMID 32211401, 2020).
NUT carcinoma (1 paper, 2020). "KEY POINTS: Metastatic NUT carcinoma can show diffuse vimentin positivity and focal neuroendocrine marker positivity." (PMID 32319714, 2020).
oral candidiasis (1 paper, 2022). Infection of the mucosal lining of the mouth with the fungus Candida albicans. "Oral candidiasis increases p63 and vimentin expression and decreases E-cadherin expression in OSCC histopathological specimens." (PMID 35089096, 2022). "The increased p63 and vimentin expression and decreased E-cadherin expression in the Candida-colonized tumors indicate that C. albicans can drive an EMT phenotype, which may lead to a poor prognosis for oral candidiasis-associated OSCC." (PMID 35089096, 2022).
orchitis (1 paper, 2024). Inflammation of one or both testes due to viral or bacterial infections. "The present study investigated the link between vimentin expression level and SARS-CoV-2-induced orchitis." (PMID 39866583, 2024).
ovarian angiosarcoma (1 paper, 2025). A malignant vascular neoplasm arising from the ovary. "By immunohistochemistry, the most common markers expressed in ovarian angiosarcoma, primary and secondary, include CD31 (100%), CD34 (98%), vimentin (100%), and factor VIII-related gene (85.7%)." (PMID 41322900, 2025).
ovarian mucinous cancers (1 paper, 2025). "Similarly, IHC markers progesterone receptor and vimentin have been reported to improve classification accuracy of ovarian mucinous cancers but were not evaluated in this study." (PMID 40981433, 2025).
pancolitis (1 paper, 2019). Ulcerative colitis that involves the entire colon. "Increased levels of K8, K18, and K19 and VIM in longstanding pancolitis in remission were noted relative to controls and recent-onset colitis in remission." (PMID 30774653, 2019).
Papillary Craniopharyngioma (1 paper, 2021). A craniopharyngioma composed of sheets of squamous epithelium which separate to form pseudopapillae. "As expected, these animals developed identifiable, well-circumscribed tumors which were clearly positive for tdTomato and Vimentin, suggesting the origin of papillary craniopharyngioma-like neoplasm from Rax+ tanycytes." (PMID 33863883, 2021).
parvovirus infection (1 paper, 2022). "Fay and Panté reported that vimentin is required for parvovirus infection in which vimentin mediates endosomal trafficking of viral particle." (PMID 35656400, 2022).
pericardial mesothelioma (1 paper, 2026). "Autopsy, histopathology and immunohistochemistry (positive for cytokeratin AE1/AE3, vimentin, calretinin and HBME-1) confirmed pericardial mesothelioma with pleural dissemination." (PMID 41902876, 2026).
perineurioma (1 paper, 2024). A usually benign perineurioma not associated with a nerve, arising from the soft tissues. "Regardless of localization and morphologic subtypes, perineuriomas immunohistochemically are characterized by the expression of vimentin, EMA, Glut-1, and claudin-1." (PMID 39412332, 2024).
pheochromocytoma (1 paper, 2024). "An immunohistochemical study indicated that this tumor was pheochromocytoma because of the neuroendocrine markers, such as vimentin, synaptophysin, S100, pan CK, and CD-56." (PMID 39290924, 2024).
Pilomatricomas (1 paper, 2016). "Pilomatricomas resulting from Ctnnb1 activation in Lgr5-expressing stem cells were surrounded by an increased density of vimentin+ fibroblasts, while fibroblast density in the rest of the skin was unaffected." (PMID 26771241, 2016).
plasmacytoma (1 paper, 2017). Plasmacytoma is a localized mass of neoplastic monoclonal plasma cells that represents approximately 5% of all plasma cell neoplasms. "Pathology revealed typical histology of plasmacytoma and immunohistochemistry revealed the expression of CD138, CD45, vimentin, and Kappa light chain." (PMID 28178171, 2017).
Pneumocystis pneumonia (1 paper, 2024). "characterized B lymphocyte-derived exosomes in fatal Pneumocystis pneumonia (PCP) and found significant alterations in histone H1.3, vimentin, and tyrosine protein phosphatase non-receptor type 6 (PTPN6) levels." (PMID 38994350, 2024).
polyarthritis (1 paper, 2013). "Three (3.2%) JIA patients reacted with native vimentin aa 59–74, including one with IgM RF-positive polyarthritis and one with oligoarthritis." (PMID 23987731, 2013). "Two (2.1%) JIA patients reacted with native vimentin aa 1–16, including one with IgM RF-positive polyarthritis, one with IgM RF-negative polyarthritis and one with oligoarthritis." (PMID 23987731, 2013).
polycystic kidney disease (1 paper, 2015). A usually autosomal dominant and less frequently autosomal recessive genetic disorder characterized by the presence of numerous cysts in the kidneys leading to end-stage renal failure. "Epithelial mesenchymal transition has also been implicated in the pathogenesis of polycystic kidney disease and the mesenchymal marker vimentin has been found in cystic epithelia in the PCK rat." (PMID 26136112, 2015).
posterior pituitary tumour (1 paper, 2019). "Tumours were also negative for vimentin, expressed by spindle cell oncocytoma, an uncommitted posterior pituitary tumour." (PMID 30912742, 2019).
premature aging syndrome (1 paper, 2022). Changes in the organism associated with senescence, occurring at an accelerated rate. "Interestingly, a mutant variant of vimentin, found in a patient with a premature aging syndrome, promoted the generation of an N‐terminal cleaved form, and faster protein turn‐over." (PMID 35122388, 2022).
prostatic leiomyoma (1 paper, 2013). "In contrast with prostatic leiomyoma with atypia, these cells are intensely immunoreactive for vimentin instead of desmin and actin." (PMID 23781384, 2013).
pulmonary edema (1 paper, 2022). Accumulation of fluid in the lung tissues causing disturbance of the gas exchange that may lead to respiratory failure. "To explore pharmacological mechanisms underlying PN-OP in pulmonary edema, we assessed the impact of various drugs and their effective levels on the vimentin tension and PN-OP in alveolar epithelial cells after AngII or BK stimulation." (PMID 35794575, 2022).
pyometra (1 paper, 2020). "S100A12, vimentin, and Hp were the proteins most up-regulated in canine pyometra." (PMID 32596263, 2020).
radiation fibrosis (1 paper, 2026). "In addition to H&E, CD68 immunohistochemistry was used to assess macrophage infiltration, and vimentin staining identified mesenchymal cells, particularly activated fibroblasts, to evaluate post-radiation fibrosis." (PMID 41552761, 2026).
Rb (1 paper, 2021). "In details, we found that E-cadherin expression was increased, while vimentin and N-cadherin expressions were decreased after overexpressing miR-491-3p in Rb cells." (PMID 33098307, 2021). "Protein expression of the E-cadherin from the 15 Rb patients was significantly decreased in tumors, whereas N-cadherin and Vimentin expressions were significantly increased as compared to normal ARPE-19 cell." (PMID 33098307, 2021).
rectal tumor (1 paper, 2020). "The GAPDH and PUM1 combination was used successfully for normalization in the experiment related to the CSCs and EMT markers ALDH1, E cadherin, vimentin, and Twist expression in rectal tumors." (PMID 33457124, 2020). "Similarly, when metastatic rectal cancer cases were compared with stage II rectal tumors, a 7.14-fold difference in ALDH1, -1.22-fold change in E cadherin, 2.07-fold change in vimentin, and 5.05-fold change in Twist (P=0.015) were reported." (PMID 33457124, 2020).
renal dysplasia (1 paper, 2020). Renal dysplasia is a form of renal malformation in which the kidney(s) are present but their development is abnormal and incomplete. "Further, our results show that in human renal dysplasia, beta-catenin, vimentin, and e-cadherin also have abnormal expression patterns." (PMID 32555682, 2020). "Taken together, these findings confirm that abnormalities in the expression of vimentin and E-cadherin are also a feature in human renal dysplasia." (PMID 32555682, 2020). "We next determined if the observations of disrupted vimentin and E-cadherin expression in our mouse model is consistent in human renal dysplasia." (PMID 32555682, 2020).
renal fibrosarcoma (1 paper, 2026). "Immunohistochemistry showed diffuse vimentin positivity with negative staining for epithelial, myogenic, neural, and renal lineage markers, confirming the diagnosis of high-grade primary renal fibrosarcoma." (PMID 41552272, 2026).
renal osteosarcoma (1 paper, 2022). "Immunohistochemical analysis of primary renal osteosarcoma is positive of vimentin and muscle‐specific actin." (PMID 35756392, 2022).